KCTD14 (potassium channel tetramerization domain containing 14)
Synonyms: MGC2376
Tractability: PROTAC: ubiquitination databases record sites on it.
Gene: Protein-coding gene on chromosome 11 (78,015,715 to 78,046,191, reverse strand). Ensembl gene ENSG00000151364.
Subcellular location (Human Protein Atlas): Nucleoplasm; Cytosol; Vesicles
Gene Ontology:
Molecular function: protein binding
Biological process: protein homooligomerization
Genetic constraint (gnomAD): Loss-of-function variants: 6 observed, 3.91 expected, observed/expected ratio (o/e) 1.53, 90% interval 0.76 to 1.93. That is too few expected variants to judge how well the gene tolerates losing a copy. Missense variants: 341 observed, 340.02 expected, observed/expected ratio (o/e) 1, 90% interval 0.92 to 1.1. Synonymous variants: 140 observed, 136.06 expected, observed/expected ratio (o/e) 1.03, 90% interval 0.9 to 1.18.
Homologues: Orthologues: chimpanzee KCTD14 (100% identical), macaque KCTD14 (98% identical), guinea pig KCTD14 (58% identical), rat Kctd14 (55% identical), mouse Kctd14 (54% identical), rabbit KCTD14 (53% identical), tropical clawed frog kctd14 (44% identical), zebrafish kctd14 (44% identical), Drosophila melanogaster twz (16% identical), Caenorhabditis elegans F32B4.5 (13% identical). Paralogues in human: KCTD7 (30% identical), KCTD8 (25% identical), KCTD16 (24% identical), KCTD12 (24% identical), KCTD19 (20% identical), KCTD21 (20% identical), KCTD11 (20% identical), KCTD18 (20% identical), KCNRG (19% identical), KCTD6 (18% identical), KCTD15 (18% identical), KCTD1 (17% identical), and 1 more.
Diseases named in the same sentence as KCTD14 in open-access papers:
KCTD14 is named in the same sentence as 4 diseases in open-access papers, as found by Europe PMC text mining. Sharing a sentence is not in itself a finding about the gene and the disease. The quoted sentences say what the papers report.
breast carcinoma (1 paper, 2023). "The expressions of FUNDC2 and KCTD14 in luminal subtype breast cancer tissues and TNBC tissues were statistically different (P<0.05)." (PMID 37700593, 2023). "However, we found that the expression of KCTD14 was not significantly different between breast cancer tissue and adjacent tissue, and KCTD14 expression was positively correlated with TNBC progression-free survival." (PMID 37700593, 2023). "Therefore, we focused our research on KCTD14 and FUNDC2, which might be novel targets in breast cancer, especially TNBC." (PMID 37700593, 2023). "Immunohistochemical EliVision method was used to detect the expressions of KCTD14 and FUNDC2 in 82 luminal subtype breast cancer tissues, 58 TNBC paraffin tissue samples and 33 nontumor benign lesions." (PMID 37700593, 2023).
ovary cancers (1 paper, 2021). "KCTD14 has not so far been investigated, and involvement in the onset and progression of cancer has not been documented, DB analysis suggests a potential protumor role in ovary cancers: COSMIC reports a CNV gain in 4.5% of ovary cancers and GENT2 a FC = 1.5 (p value < 0.001) in expression." (PMID 34001146, 2021).
KCTD14 also shares sentences with these, for which no sentence is quoted: pancreatic cancer (1 paper); prostate carcinoma (1).